GJB2 (gap junction protein beta 2)
Diseases named in the same sentence as GJB2 in open-access papers (continued):
Sharing a sentence is not in itself a finding about the gene and the disease.
hearing loss (continued). "Individuals experiencing hearing loss carried a heterozygous del(125 kb) in combination with a monoallelic pathogenic GJB2 variant in trans configuration, whereas their parents who carried either a heterozygous del(125 kb) or a pathogenic GJB2 variant exhibited no hearing impairment." (PMID 40225913, 2024). "Finding a genetic diagnosis for one out of 14 subjects with alleged non-syndromic uSNHL as in the present study may still be motivated, but as the risk of progression is low for GJB2/connexin 26-related hearing loss (about 90% are stable over time) it may not be high priority." (PMID 36675424, 2023). "In the families of patients with a heterozygous pathogenic GJB2 variant, the extended Sanger sequencing and WES could clarify the cause of hearing loss in 22% of the patients while enabling precise genetic counselling and an estimation of the risk of hearing loss recurrence in their relatives." (PMID 34062854, 2021). "Even though the GJB2 gene is of great importance in the etiology of non-syndromic sensorineural impairment, there are so far very few studies describing the audiometric characteristics of patients with mutations in the GJB2 gene associated with hearing loss, especially in Brazil." (PMID 18278224, 2007). "Given these concordant data on the involvement of PJVK gene in hearing impairment, we next investigated the implication of this gene in Mauritanian patients negative for the GJB2 and LRTOMT genes." (PMID 39230647, 2025). "For the four deafness-related genes tested, including SLC26A4, GJB2, GJB3 and mtDNA 1555 and 1494, no pathological variants were found, indicating the origin of hearing loss from the pathological nature of GA-1." (PMID 33256818, 2020). "Biallelic GJB2 PLP variants were the most common and widespread variants associated with non-syndromic hearing impairment (NSHI) in different global populations but absent in most African populations." (PMID 33126609, 2020). "Moreover, no pathogenic mutations in GJB2 were found in a cohort of 44 probands from Nigeria with non-syndromic deafness, and only 7% of a cohort of 127 American probands of Hispanic or African descent with bilateral non-syndromic hearing impairment presented a disease causing mutation in GJB2." (PMID 31731535, 2019). "Our study aimed to investigate GJB2 (connexin 26) and GJB6 (connexin 30) mutations associated with non-syndromic childhood hearing impairment (HI) as well as the environmental causes of HI in Ghana." (PMID 31620164, 2019). "This study confirmed that mutations in the GJB2 gene and the del(GJB6-D13S1830) deletion are not implicated in familial non-syndromic hearing impairment in Cameroon." (PMID 31731535, 2019). "Reverse dot blotting for 16 hotspot variants in the GJB2, GJB3, SLC26A4, and MTRNR1 genes was performed to rule out common variants in hereditary hearing loss." (PMID 30068307, 2018). "Connexin26 (Cx26, GJB2) gene mutations are responsible for >50% of nonsyndromic hearing loss, causing either congenital deafness or late-onset progressive hearing loss." (PMID 28603488, 2017). "Nevertheless, the high rate of bi-allelic mutations in patients with sporadic profound hearing loss implies that sporadic congenital hearing loss is caused in a majority of cases in Korea by SLC26A4 mutations and not by GJB2 mutations." (PMID 28383030, 2017). "We and others have reported 223 different mutations in GJB2 and GJB6 associated with hearing impairment but not with skin abnormalities in Argentina." (PMID 27141831, 2016). "Connexin 26 (Cx26, GJB2) mutations are a common genetic cause for non-syndromic hearing loss and are responsible for ~50% of non-syndromic hearing loss in children." (PMID 26074771, 2015). "No homozygous or compound heterozygous mutation of the GJB2 or SLC26A4 gene was found, and the mitochondrial m.1555A > G homogeneous mutation were responsible for hearing loss in 1.75% of 114 Tibetan patients." (PMID 24612839, 2014).
hearing loss (continued). "Although our initial aim was to evaluate the effect of GJB2 and GJB6 mutations on the outcome of CI in children with congenital hearing loss, our patient population appeared to have no GJB6 mutation." (PMID 22567367, 2011). "In hearing loss patients negative of GJB2, SLC26A4, and mitochondrial 12S rRNA, Usher and Waardenburg syndrome-related genes account for a major proportion in Chinese Han families, followed by STRC causing mild to moderate hearing loss." (PMID 36504663, 2022). "GJB2 and GJB6 mutations account for up to 50% of all nonsyndromic hearing loss cases." (PMID 35110999, 2021). "Although GJB2 and SLC26A4 mutations were absent in our patients, our results show that CDH23 mutation caused ARNSHL in 2 of 13 (15%) affected Korean families and that 3 of 93 patients with hearing loss carried a heterozygous mutation." (PMID 24767429, 2014). "In most regions, even basic screenings like GJB2/GJB6 are not available, and worse, numerous individuals with hearing impairment lack access to proper rehabilitation or genetic services." (PMID 38397168, 2024). "Our findings support previous reports that GJB2 and GJB6 do not play a significant role in non-syndromic hearing impairment in most populations of African descent." (PMID 31731535, 2019).
deafness (372 papers, 2004 to 2026). An inherited or acquired condition characterized by the complete loss of the ability to hear from one or both ears. "Regarding hearing-specific variables, later-onset deafness, a shorter duration of deafness, and identifiable etiologies (notably specific genetic mutations such as GJB2 and OTOF) exert significant influence." (PMID 41682664, 2026). "Over the past decade, major advancements in auditory genetics and vectorology have transformed the potential for treating genetic hearing loss, paving the way for precision interventions for GJB2-related deafness." (PMID 41516362, 2026). "In contrast, mice with conditional loss of Gjb2 in supporting cells exhibit extensive loss of hair cells and neurons and rapidly progress to profound deafness." (PMID 41227304, 2025). "The GJB2 gene is mostly associated with recessive mutations leading to non-syndromic deafness, while a smaller portion involves dominant missense mutations causing syndromic deafness, such as the keratitis-ichthyosis-deafness (KID) syndrome." (PMID 41049429, 2025). "Twenty subjects had GJB2 mutations associated with deafness, while twenty had GJB2-unrelated deafness." (PMID 40004458, 2025). "The genetic pattern of GJB2 is mainly autosomal recessive inheritance, among which c.235delC, c.299‐300delAT, and c.109G > A are common hot spot mutations in Chinese deafness." (PMID 40777882, 2025). "In the Taiwanese population, the most common deafness mutations are GJB2 c.109G>A (p.V37I) and GJB2 c.235delC (p.L79CfsTer3)." (PMID 40943139, 2025). "Through a detailed analysis of the genotypes and phenotypes of family members, we found a strong association between the GJB2 c.551G>A mutation and the hereditary deafness phenotype within the family." (PMID 40336802, 2025). "A well-written review by Morton and Nance attributes 44% of hearing loss at birth to syndromic or non-syndromic deafness, 21% to GJB2 gene mutation, and 3% to Pendred syndrome." (PMID 40283619, 2025). "To date, a total of 453 GJB2 variants have been identified, of which more than 380 variants have been associated with deafness." (PMID 39757988, 2025). "A significant finding was the identification of 11 neonates carrying pathogenic variants in two different deafness genes (e.g., GJB2 and SLC26A4, GJB2 and 12S rRNA, etc.)." (PMID 41181184, 2025). "For example, it is well known that deafness can be caused by GJB2 gene mutations (omim.org), while individuals with a GJB2 knockout exhibit normal audiometry." (PMID 40533538, 2025). "In Taiwan, common deafness-associated genes include GJB2, SLC26A4, OTOF, MYO15A, and MTRNR1, which were similar to those found in other populations." (PMID 40943139, 2025). "Previous cohort studies identified a recurrent variant in GJB2 (c.35delG) estimated to account for approximately 60-70% of deafness in European, North African, Middle Eastern, Asian, North and South American populations." (PMID 38486023, 2025). "In China, approximately 70% of hereditary deafness originates from four common deafness-causing genes: GJB2, SLC26A4, GJB3, and MT-RNR1." (PMID 38172427, 2024). "Our results highlight the unique genetic landscape of SNHI in this population, which shows a lower prevalence of GJB2 mutations and a higher frequency of variants in other deafness-related genes." (PMID 39336818, 2024). "The study examined 9 deafness-causing hotspots in the 4 most common genes: GJB2(c.35delG, c.176del16, c.235delC, and c.299delAT), GJB3(c.538C>T), SLC26A4(c." (PMID 39287240, 2024). "Both methods found GJB2 to be the most common deafness gene, followed by SLC26A4 and mtDNA, GJB3 variants were rare, with positive rates of 2.2%, 1.38%, 0.42%, and 0.18%, respectively, consistent with other reports." (PMID 38172182, 2024). "In the study of local adaptation, we found that a risk variant rs72474224 in the GJB2 gene is associated with deafness and underlying positive selection in the HM populations." (PMID 38475771, 2024).
deafness (continued). "The most common deafness gene was GJB2, with c.109G>A as its hotspot variant, followed by SLC26A4, and c.919-2A>G as its hotspot variant." (PMID 38172182, 2024). "GJB2 encodes a gap-junction protein (connexin) whose autosomal recessive allele causes deafness in Asian populations." (PMID 38177502, 2024). "In this study, 9 known hotspot mutations associated with the 4 most common deafness genes were investigated: GJB2 c.35delG, c.176del16, c.235delC, and c.299delAT; GJB3 c.538C>T; SLC26A4 c." (PMID 39287240, 2024). "In conclusion, our study has revealed a new variant, c.188delT, within the GJB2 gene in a Chinese family with a newborn suffering from deafness." (PMID 39151510, 2024). "Common pathogenic mutations in patients with non-syndromic deafness in Changzhou were concentrated in GJB2 (c.235delC, c.299_300delAT, and c.176-191del16) and SLC26A4 (c.919-2A > G and c.2168 A > G)." (PMID 38172427, 2024). "We identified highly differentiated variants between HM and Han Chinese, in particular, a deafness-related missense variant (rs72474224) in the GJB2 gene is in a higher frequency in HM speakers than in others." (PMID 38475771, 2024). "In Taiwan, the common deafness-associated genes assessed, in order of prevalence included GJB2, SLC26A4, OTOF, MYO15A, and MT-RNR1." (PMID 38840095, 2024). "Critical mutations that occur in genes linked to deafness, such as GJB2, SLC26A4, GJB3, and 12s rRNA, hold considerable importance." (PMID 39151510, 2024). "For example, patients with deafness associated with GJB2 or SLC26A4 have a good prognosis after cochlear implantation." (PMID 38172182, 2024). "On the other hand, GJB2 mutations result in new features that disrupt the epidermal homeostasis, classifying these disorders as gain-of-function diseases in syndromic deafness cases." (PMID 38827992, 2024). "Second is a splice-site variant in GJB2 (rs80338940; category 1; c.-23+1G>A), a gene related to autosomal recessive deafness (MIM# 220290) where the only homozygous carrier of the variant in the biobank was reported to be using a hearing aid." (PMID 38584274, 2024). "The most common deafness gene was GJB2, with c.235delC as its hotspot variant, followed by SLC26A4 and c.919-2A>G, as its hotspot variant." (PMID 38172182, 2024). "For instance, GJB2 is the most common deafness gene causing autosomal recessive nonsyndromic hearing loss (DFNB1A, OMIM #220290)." (PMID 40225913, 2024). "Mutations within the GJB2 gene can cause 2 types of deafness: autosomal recessive deafness DFNB1A and autosomal dominant deafness 3A (OMIM #601544)." (PMID 39151510, 2024). "In particular, we have also found mutations such as rs72474224 ((p.Val37Ile, GJB2) that are associated with deafness in the HM population are in high frequency, indicating the medical potential of genetic research on minority populations." (PMID 38475771, 2024). "In Mongolia, previous studies have shown a lower prevalence of GJB2 mutations and a higher frequency of variants in other deafness-related genes." (PMID 39336818, 2024). "These include (i) rs113993960 variant in CFTR leading to the deletion of a crucial F508 residue of the CFTR protein, and (ii) rs80338939 variant in GJB2 linked to hearing loss and deafness." (PMID 39498263, 2024). "These cells expressed several causal genes for various deafness forms, including Eps8l2, Gjb2, Gjb6, Homer2, Coch, Clic5, Dcdc2a, Pou3f4, Col4a6, and Six1." (PMID 37339214, 2023). "In 2023, the GJB2 gene p.V37I mutation will be incorporated into deafness genetic screening in Beijing." (PMID 37732008, 2023). "The GJB2 locus has been associated with recessively inherited forms of deafness and is thought to have been selected for potential advantage related to epidermal thickening or increased cell survival." (PMID 37479695, 2023). "Disease associated with connexin abnormalities such as GJB2 have been reported in deafness and cardiac disease." (PMID 37648762, 2023).
deafness (continued). "The other is a deafness‐related variant associated with Connexin‐26 (Cx‐26), which is the gap connection protein responsible for signal transmission and material exchange between adjacent cells and encoded by the gap junction protein beta 2 (GJB2) gene." (PMID 36916028, 2023). "In this study, the most heterozygous pathogenic mutations in GJB2 was c.109G > A (p.Val37Ile), which has been confirmed to be pathogenic for Autosomal Recessive Deafness 1 A (DFNB1A)." (PMID 37147621, 2023). "A systematic study of the effects on the protein functions of all of the GJB2 missense variants will provide a basis for understanding the molecular mechanisms by which the GJB2 missense variants lead to different clinical deafness phenotypes." (PMID 37106706, 2023). "Prior studies revealed that loss of function variants in Gjb2 impair the structural development of the cochlea and result in deafness." (PMID 37368868, 2023). "Mutations in GJB2 (Gap junction protein beta 2) are the most common genetic cause of non-syndromic hereditary deafness in humans, especially the 35delG and 235delC mutations." (PMID 37178259, 2023). "The gene variant GJB2 c.109G:&gt;A is found in people with mild to moderate deafness, but the disease is inherited according to an autosomal recessive model—our proband is the carrier of this variant." (PMID 37189872, 2023). "Sensory epithelial damage is considered to be one of the main causes of deafness caused by GJB2 gene mutation." (PMID 35688810, 2022). "To uncover the roles of nuclear gene mutations in deafness, we screened for the mutations in common deafness-associated genes (GJB2, GJB3, GJB6 SLC26A4 and TRMU) in the matrilineal relatives of the HZD055 and HZD510 pedigrees." (PMID 36292680, 2022). "In our study, GJB2 was the most prevalent deafness-associated gene, with the carrier rate of the four screened variants accounting for nearly 45.14% (529/1,172) of all the positive samples (p < 0.05)." (PMID 36389375, 2022). "The study indicates that, after the GJB2 gene which is the majority of mild to moderate inherited deafness, STRC deletion accounts for the second most common cause." (PMID 36504663, 2022). "So far, CNVs have been reported in 29 non-syndromic HL-related genes, with STRC, OTOA, and GJB2/GJB6 being the most well-known genes with deafness-causing CNVs." (PMID 35710363, 2022). "In the rare heterogeneous KID syndrome (keratitis, ichthyosis, and deafness), mainly caused by mutations in the connexin 26 (GJB2) gene, 15% of patients develop squamous cell carcinoma, often in sun-exposed areas." (PMID 35887984, 2022). "Mutations in the GJB2 gene that encodes connexin 26 (Cx26) are the predominant cause of prelingual hereditary deafness, and the most frequently encountered variants cause complete loss of protein function." (PMID 35308122, 2022). "Recent studies have shown that multiple pathological mechanisms are involved in Gjb2 mutation-related hereditary deafness, in which sensory epithelial damage is considered to be a recognized cause of deafness." (PMID 35688810, 2022). "Pathogenic variants in most deafness genes, including GJB2, SLC26A4, OTOF, MTRNR1, COCH, and MYH9, have been associated with favorable outcomes, probably because the pathology is confined to the inner ear." (PMID 36009393, 2022). "GJB2 235 del C was also observed to be the most common deafness-associated mutation in the Yongchuan district of the Chongqing area in a previous study, and it was also found to have a high allele frequency in our study." (PMID 33907123, 2021). "After exclusion of the three most frequently mutated deafness genes in Tunisia: GJB2, TMC1, and SLC26A4 genes, ES was carried out for the index case TNDF182-3." (PMID 34614013, 2021). "Case samples with homozygous genotype for the mentioned deletion also compound heterozygotes carrying del (GJB6-D13S1830) and deafness-causing allele variant of GJB2 have confirmed with severe to profound congenital HL." (PMID 33912482, 2021).